BRCA1 (BRCA1 DNA repair associated)
Diseases named in the same sentence as BRCA1 in open-access papers (continued):
Sharing a sentence is not in itself a finding about the gene and the disease.
cancer (continued). "In patients selected by family history, the analysis of the cancer IHC phenotype allows the prediction of the BRCA1 genotype with a very high sensitivity and specificity." (PMID 19818148, 2009). "BRCA1 cancers with positive HIF-1α or cytoplasmic FIH had a significantly shorter relapse-free survival (P=0.007 and P=0.049, respectively)." (PMID 19724277, 2009). "The remaining 1492 were members of a family in which an affected woman (i.e., with a previous diagnosis of cancer) had undergone testing for BRCA1 and BRCA2." (PMID 19088722, 2009). "In eight recurrences that followed six primary carcinomas with low BRCA1 expression, 2 had similar and six (75%) had increased BRCA1 expression in the recurrence." (PMID 19602291, 2009). "Stage I carcinomas were more likely to have normal BRCA1 protein expression compared to stage II-IV carcinomas (p = 0.03, Fisher exact, two-tailed)." (PMID 19602291, 2009). "Both serous stage I carcinomas had normal BRCA1 protein expression and 2/3 of endometrioid stage II carcinomas had low BRCA1 protein expression." (PMID 19602291, 2009). "In 16 carcinomas recurring after 13 primaries with normal BRCA1 expression, 13(81%) maintained similar protein expression and three (19%) demonstrated decreased BRCA1 expression in the recurrence." (PMID 19602291, 2009). "We reviewed 385 unrelated families (223 with BRCA1 and 162 with BRCA2 mutations) ascertained through two regional cancer genetics services." (PMID 18513387, 2008). "Pathway analysis confirming altered expression of cancer, cell proliferation and cell cycle pathways in BRCA1 and BRCA2 mutation carrier groups is consistent with the known functions of BRCA1 and BRCA2." (PMID 18497862, 2008). "These in vivo tumorigenesis studies for both cell types indicate that Brca1 cells bearing distinct cancer stem cell markers are enriched at least 50-fold to 100-fold in tumor-initiating cells." (PMID 18241344, 2008). "BRCA1 and BRCA2 mutations are associated with increased risk of cancer at several sites other than female breast and ovary." (PMID 18349832, 2008). "There is compelling data that pathogenic mutations in BRCA1 result in a distinct tumour phenotype, whereas more subtle similarities are seen between BRCA2 cases and among familial non-BRCA1/BRCA2 cancers." (PMID 19094228, 2008). "In our study CK-5/6 positivity was detected in a large proportion (33%) of the 167 ER/HER2-negative cancers as well, but only in 25% of the 20 ER/HER2-negative and BRCA1-related cancers." (PMID 18275599, 2008). "Population-based studies have shown that mutations in BRCA1 and BRCA2 confer an increased risk of breast, ovarian and other cancers." (PMID 19102775, 2008). "Only 14.5% of BRCA1-related cancers were ERα-positive compared with 57.5% in the control group (P < 0.0001)." (PMID 18405391, 2008). "The most effective, independent predictors of BRCA1 mutations were age at onset, HER2 status, and either ER or PR status, as compared with sporadic or non-BRCA1/BRCA2 cancers." (PMID 18275599, 2008). "Here, we found that addition of 17-DMAG simultaneously or after chemotherapeutic agents sensitizes Brca1 cancer stem cells to three types of DNA-damaging agents: doxorubicin, cisplatin, and etoposide." (PMID 18241344, 2008). "We compared numbers and stages at diagnoses of incident interval cancers with incident screen-detected cancers in a consecutive series of 888 BRCA1/2 carriers." (PMID 17426707, 2007). "In summary, this study includes men and women, unaffected by cancer at the time of genetic testing, attending nine genetic centres undertaking the majority of BRCA1/BRCA2 testing in clinical settings across the UK." (PMID 17285126, 2007). "In the following decade, as BRCA1 and BRCA2 testing became more common in patients with a personal or family history of cancer, numerous studies assessed cancer risks in carriers of these mutations." (PMID 17213823, 2007).
cancer (continued). "All of these findings indicate that BRCA1 status is very important in the sensitivity to cisplatin in various cancer cells." (PMID 19690636, 2007). "The prevailing view on the mechanism by which heterozygous mutations in the BRCA1 and BRCA2 genes predispose to cancer is that they provide an unstable genetic environment in which further mutations leading to tumorigenesis are more likely to occur." (PMID 16538216, 2006). "In contrast to BRCA1 tumours, the BRCA2 tumours diagnosed in patients 50 years or older were more often ER- (52.6% vs 25.6%, P = 0.02) and PR- (80.0% vs 54.4%, P = 0.036) than non-BRCA1/2 cancers among the same age group." (PMID 15987451, 2005). "In our study, all patients carried the most common, easily detectable mutations of BRCA1 or BRCA2 that prevail in this region and can be associated with early onset cancer." (PMID 16168118, 2005). "In comparison with BRCA1 or BRCA2 cancers, familial non-BRCA1/2 cancers represented a much greater number of ER-positive and PgR-positive cases; however, in comparison with the unselected control group they were more receptor-negative." (PMID 15642173, 2005). "Jones and colleagues have shown that tamoxifen can be an agonist for the outgrowth of ER- hyperplasias and cancers in the MMTV-Cre Brca1 conditional exon 11 deletion model." (PMID 16457695, 2005). "When compared with familial non-BRCA1/2 cancers, the BRCA2-associated cancers were diagnosed at a younger age (median age 47 years; among non-BRCA1/2 patients the median age was 55 years; P ≤ 0.0005)." (PMID 15642173, 2005). "In comparison with familial non-BRCA1/2 cancers (median age 55 years), a univariate analysis of BRCA1 tumours showed similar differences from unselected cancers." (PMID 15642173, 2005). "In this study, we specifically sought to compare BRCA1 cancers with familial non-BRCA1/2 cancers as well, which is the relevant question in a clinical and genetic counselling setting." (PMID 15642173, 2005). "We performed mutation screening of the complete coding region of BRCA1 and BRCA2 in 349 unrelated Belgian families referred to our family cancer clinic and report here the nature and distribution of the mutations identified." (PMID 15026808, 2004). "Intriguing parallels exist between expression characteristics of cancer testis antigens and expression changes mediated by BRCA1." (PMID 15383145, 2004). "Several genes including tumour suppressor genes and DNA repair genes such as hMLH1, RB1, VHL, p15, p16, RASSF1A, MGMT and BRCA1 in human cancers were shown to be epigenetically inactivated by DNA methylation in tumours." (PMID 14970867, 2004). "Two recent reports demonstrated that BRCA1 and BRCA2-associated tumors have distinct expression profiles in both breast and ovarian cancers." (PMID 15383145, 2004). "Genes involved in DNA repair, especially those that interact with the product of the BRCA1 or BRCA2 genes, are of particular interest as cancer risk modifiers in BRCA1/2 mutation carriers." (PMID 15138485, 2004). "Our study permits to estimate the prevalence of BRCA1 and BRCA2 mutations in a Belgian patient population referred to a family cancer clinic." (PMID 15026808, 2004). "We have previously reported the results of mutation analysis of BRCA1 and BRCA2 cancer predisposition genes in a cohort of radiation-hypersensitive cancer patients." (PMID 12698192, 2003). "Degradation by a cathepsin-like protease in fine balance with BRCA1 transcription is responsible for maintaining the low steady-state level of BRCA1 protein seen in many cancer cells." (PMID 12838319, 2003). "Mutations in BRCA1 and BRCA2 genes are observed in breast, ovarian, and other cancers." (PMID 41741471, 2026).
cancer (continued). "In BRCA1/2‐mutant cancers, SL strategies have primarily focused on PARPis." (PMID 41537447, 2026). "Another international, longitudinal cohort study enrolled 4,332 women with P/LP BRCA1 or BRCA2 variants but who had never had any cancer diagnosis." (PMID 41488281, 2026). "Cancer initiation is linked to mutagenesis and loss of heterozygosity (LOH) in BRCA1 carriers." (PMID 41896346, 2026). "We highlight recent discoveries including BRCA1-dependent ubiquitination of GPX4 and its implications for PARP inhibitor synthetic lethality, NR1D2-mediated transcriptional repression of FSP1, and stromal protection conferred by cancer-associated fibroblasts." (PMID 42231453, 2026). "In BRCA-associated cancers, biallelic inactivation of BRCA1/2 markedly affects HRD score, while in non-BRCA cancers, other mechanisms are involved." (PMID 40420266, 2025). "Interestingly, among patients with a family history of cancer, 63% expressed BRCA1 were with 1+ (80%) and 2+ (20%) staining intensities." (PMID 40224184, 2025). "Furthermore, we treated carriers of BRCA1/2 variants of uncertain significance (VUS) as having the same risk as BRCA1/2 wild-type individuals, consistent with current guidelines that classify VUS as uninformative for cancer risk stratification and management." (PMID 40567951, 2025). "No family member of the proband suffered from cancer within the clinical spectrum of the BRCA1-associated tumors." (PMID 41375073, 2025). "A rewiring of Glu metabolism may also contribute to polyamine synthesis since glutamine was kept away from FA production in BRCA1-expressing cancer cells." (PMID 40863152, 2025). "A recent study analyzed germline exomes from two MM cohorts (895 and 786 individuals) revealed that MM patients are more likely than healthy individuals to carry pathogenic germline variants (PGVs) in BRCA1 (OR = 3.9) and BRCA2 (OR = 7.0) genes, which significantly increase cancer risk." (PMID 40047910, 2025). "Research shows BRCA1 and BRCA2 play vital roles not only in DNA repair and homologous recombination but also in germ cell development and function, potentially explaining how these mutations influence cancer risk." (PMID 41584579, 2025). "This may partly be attributed to shared genetic predispositions, including mutations in genes like BRCA1, BRCA2, MLH1 and MLH2, which are associated with susceptibility to both cancers." (PMID 40444502, 2025). "Our findings provide a preclinical rationale for assessing ADAR1-targeting agents in BRCA1/2-mutant cancers, and introduces a conceptually novel approach to synthetic lethal treatments, which exploits tumor cell-intrinsic cytosolic immunity as a targetable vulnerability of cancer cells." (PMID 40730818, 2025). "In addition to this, a recent high‐throughput screening study successfully identified BRCA1‐suppressing agents that sensitize BRCA1 wild‐type cancer cells to PARPi." (PMID 40652528, 2025). "Therefore, it is understood that the genes BRCA1, BRCA2, and PALB2 are key cancer susceptibility genes." (PMID 40869938, 2025). "Against the background of these findings, it is likely that even if GCT, not belonging to the classic “BRCA1 cancer entities”, the existing germline mutation in our patient contributed to the development and progression of the NSGCT." (PMID 40519304, 2025). "This project aimed to investigate the prevalence of germline variants in the non-coding regulatory regions of BRCA1/2 and other BC predisposition genes in patients with triple-negative BC (TNBC) selected for age at cancer diagnosis and/or family history of cancer." (PMID 40338220, 2025). "Similarly, CX5461 has been used for early-stage clinical studies of BRCA1-, BRCA2-, and PALB2-mutated cancers." (PMID 41203590, 2025). "While tumor analysis did not confirm loss of heterozygosity, evidence suggests that BRCA1 haploinsufficiency also increases genomic instability and cancer risk." (PMID 40519304, 2025). "The activation of BRCA1 resulted in the suppression of cancer cells." (PMID 40650152, 2025).
cancer (continued). "Currently, risk assessment tools used do not differentiate cancer risk according to the specific BRCA1 mutation (except for the lower penetrance 5096G > A missense mutation)." (PMID 41440233, 2025). "The sociodemographic form investigated the following characteristics: age, sex, marital status, educational background, occupation, BRCA1/2 status, proband/relative status, current state of health, any previous cancer diagnosis and, if applicable, tumor site, and inclusion in a GC or MCG pathway." (PMID 40596937, 2025). "Overall, our data suggest that TLK expression is functionally linked to PARPi sensitivity in BRCA1-mutant cells and highlight the role of TLK proteins in modulating the anticancer effects of PARP inhibition, particularly in challenging cancer types such as TNBC and HGSOC." (PMID 39844055, 2025). "In this study, we characterized a unique germline genetic alteration of BRCA1, which resulted from a novel type of mechanism not reported earlier in genes associated with cancer suspicion." (PMID 41375073, 2025). "Furthermore, MSN interacts with BRCA1, colocalizing with F-actin at the plasma membrane of cancer cells." (PMID 40429863, 2025). "PARPi therapy has shown promising efficacy in the treatment of BRCA1/2-mutant cancer." (PMID 41359628, 2025). "Whether therapy with PARP inhibitors can be extended to BRCA1 promoter-methylated cancers is still under investigation." (PMID 39392573, 2025). "Moreover, DZNep treatment has selectively eliminated BRCA1-mutated cells by modifying EZH2 transcription, a crucial factor in DNA repair and cancer cell proliferation." (PMID 40136510, 2025). "Here, our study aims to screen and identify FDA-approved drug that could greatly enhance PARP inhibitors’ therapeutic efficacy in BRCA1/2-WT cancer cells." (PMID 40299557, 2025). "BRCA1/2 mutant cancers have a limited capacity to repair DSBs." (PMID 41049848, 2025). "Furthermore, LINC00894 promotes cancer cell invasion and proliferation, with high expression correlating with a worse overall survival rate due to its impact on BRCA1 pathways." (PMID 39997609, 2025). "Strikingly, 64.6% of HRD tumors in the pan-cancer dataset lacked BRCA1/2 mutations (BRCA1/2WT), underscoring the significance of our HRD classification method." (PMID 41279139, 2025). "When utilized effectively, genetic testing for cancer risk-increasing mutations, (such as pathogenic mutations in the BRCA1 and BRCA2 genes) can identify high-risk individuals prior to cancer development, allowing for tailored interventions aimed at early cancer detection and prevention." (PMID 40862808, 2025). "Ivosidenib greatly potentiated Olaparib-induced DSBs in BRCA1/2-WT or mutant cancer cells." (PMID 40299557, 2025).
cancer (continued). "In the clinic, patients with a BRCA1 or BRCA2 mutation derive a significant benefit from PARP inhibitor treatment, a finding which has been confirmed in dozens of clinical trials across multiple cancer types including ovarian, breast and prostate cancers." (PMID 40977519, 2025). "As an example, one of our samples without known alteration but with a family cancer history, had two deep intron variants predicted, in silico, as creating new alternative splicing sites in BRCA1 (new 5′ splicing site), and BRCA2 (new 3′ splicing site)." (PMID 39783935, 2025). "We have identified TLK proteins as novel regulators of NHEJ repair and PARPi sensitivity in BRCA1-depleted cells, suggesting that TLK repression may represent a previously unrecognized mechanism by which BRCA1 mutant cancers acquire PARPi resistance." (PMID 39844055, 2025). "For example, the AmpliSeq Cancer Hotspot Panel v2 does not target mutations in BRCA1/2 genes, but it can be complemented with specific panels, such as the AmpliSeq BRCA panel." (PMID 40864753, 2025). "Notably, BRCA1, BRCA2, and AURKA played significant regulatory roles within the gene expression network and are strongly implicated in cancer onset and progression." (PMID 40666234, 2025). "Combining a small molecule RAD51-BRCA2 inhibitor with PARPi could effectively target cancer cells, even when BRCA1/2 genes and HR are fully functional." (PMID 40091075, 2025). "Prophylactic mastectomy is a risk-reducing surgical procedure performed to reduce the risk of developing cancer in the other breast in patients with a family history of cancer, known genetic mutations such as BRCA1 or BRCA2, or who have been diagnosed with cancer in one breast." (PMID 39830622, 2025). "Additionally, nine (18.75%) survey takers tested positive for either BRCA1 or BRCA2 mutations, and 42 (87.5%) of patients’ cancers were hormone-positive." (PMID 41589155, 2025). "Given that DSBs represent the most biologically significant lesions induced by IR, and defective DSB repair confers cellular radiosensitivity, BRCA1/2-mutant cancer patients were hypothesized to derive substantial benefit from radiotherapy." (PMID 41213904, 2025). "Of the 18 patients with mutations in the BRCA1 and BRCA2 genes, 14 had a family history (FH) of cancer; of the 7 patients with mutations in the ATM gene, 5 had a cancer FH, and of the 34 patients with other altered genes, 27 had a cancer FH." (PMID 40259910, 2025). "Additionally, methylation of the BRCA1 gene promoter has been identified as a potentially relevant factor in metaplastic cancers." (PMID 40421084, 2025). "In cells with BRCA1 or BRCA2 mutations, which cannot repair double-strand breaks already by homologous recombination, this accumulation of DNA damage becomes lethal, causing cancer cell death." (PMID 40004231, 2025). ",47,52BRCA2-associated cancers on MRI more commonly present as masses with irregular shapes and spiculated margins and are more likely to exhibit non-mass enhancement (NME) than BRCA1-associated cancers." (PMID 41083355, 2025). "When BRCA1 is mutated or deleted, the levels of PERK and IRE1 proteins increase, leading to sustained activation of UPR, inhibition of protein folding, or UPR signaling significantly reduces the overall survival rate of BRCA1-deficient cancer cells." (PMID 41462887, 2025). "According to the Cancer Risk Estimates Related to Susceptibility (CARRIERS) Consortium, 2021, the prevalence of pathogenic variants of BRCA among women with BC was estimated to be 1·3% (associated with BRCA2) and 0·8% (associated with BRCA1)." (PMID 40626014, 2025). "Furthermore, “control” BRCA1 mutation carriers are usually obtained via the analysis of family members of patients with BRCA1-driven cancer, which creates a bias." (PMID 41374957, 2025).